IL23R (interleukin 23 receptor)
Description:
Associates with IL12RB1 to form the interleukin-23 receptor. Binds IL23 and mediates T-cells, NK cells and possibly certain macrophage/myeloid cells stimulation probably through activation of the Jak-Stat signaling cascade. IL23 functions in innate and adaptive immunity and may participate in acute response to infection in peripheral tissues. IL23 may be responsible for autoimmune inflammatory diseases and be important for tumorigenesis.
Synonyms: IL-23R; PSORS7
Tractability: Antibody: UniProt places it where antibodies can reach, with high confidence; its Gene Ontology location is reachable by antibodies, with high confidence; UniProt predicts a signal peptide or a membrane-spanning region. PROTAC: a small molecule that binds it is known.
Target class: Membrane receptor
Safety:
Unwanted effects reported when the protein is acted on. In parentheses: how it was acted on, where the effect was seen, and who reports it.
Adenoma (source: ClinPGx)
paradoxical psoriasiform reactions (source: ClinPGx)
Gene: Protein-coding gene on chromosome 1 (67,138,907 to 67,259,979, forward strand). Ensembl gene ENSG00000162594.
Subcellular location: Cell membrane
Pathways (Reactome):
Immune System: Interleukin-23 signaling; Interleukin-4 and Interleukin-13 signaling
Gene Ontology:
Molecular function: cytokine receptor activity; interleukin-12 receptor binding; interleukin-23 binding; interleukin-23 receptor activity; protein binding; cytokine binding; peptide hormone binding; prolactin receptor activity
Biological process: interleukin-23-mediated signaling pathway; negative regulation of interleukin-10 production; positive regulation of defense response to virus by host; positive regulation of interleukin-12 production; positive regulation of T-helper 1 type immune response; positive regulation of type II interferon production; response to lipopolysaccharide; response to type II interferon; cell surface receptor signaling pathway via JAK-STAT; cell surface receptor signaling pathway via STAT; cytokine-mediated signaling pathway; defense response to Gram-negative bacterium; positive regulation of activated T cell proliferation; positive regulation of cell population proliferation; positive regulation of granulocyte macrophage colony-stimulating factor production; positive regulation of interleukin-17 production; positive regulation of memory T cell differentiation; positive regulation of natural killer cell proliferation; positive regulation of NK T cell activation; positive regulation of osteoclast differentiation; positive regulation of T cell mediated cytotoxicity; positive regulation of T cell proliferation; positive regulation of T-helper 17 cell lineage commitment; positive regulation of T-helper 17 type immune response; prolactin signaling pathway
Cellular component: cell surface; interleukin-23 receptor complex; receptor complex; external side of plasma membrane; plasma membrane
Genetic constraint (gnomAD): Loss-of-function variants: 22 observed, 42.53 expected, observed/expected ratio (o/e) 0.52, 90% interval 0.37 to 0.74. The upper end of that interval is the gene's LOEUF score, 0.74, which puts it in group 3 of 6, group 1 being the genes least tolerant of losing a copy. Missense variants: 522 observed, 631.53 expected, observed/expected ratio (o/e) 0.83, 90% interval 0.77 to 0.89. Synonymous variants: 186 observed, 213.63 expected, observed/expected ratio (o/e) 0.87, 90% interval 0.77 to 0.98.
Homologues: Orthologues: chimpanzee IL23R (99% identical), macaque IL23R (94% identical), dog IL23R (85% identical), pig IL23R (82% identical), rabbit IL23R (77% identical), rat Il23r (70% identical), mouse Il23r (69% identical), zebrafish lifra (14% identical), zebrafish lifrb (14% identical), zebrafish ghra (9% identical), zebrafish il11ra (9% identical), zebrafish ghrb (8% identical), and 1 more. Paralogues in human: CSF3R (16% identical), IL6ST (16% identical), LIFR (15% identical), IL12RB2 (14% identical), IL31RA (13% identical), OSMR (13% identical), IL27RA (12% identical), PRLR (12% identical), LEPR (12% identical), CRLF1 (11% identical), GHR (10% identical), IL12RB1 (10% identical), and 11 more.
Diseases named in the same sentence as IL23R in open-access papers:
IL23R is named in the same sentence as 207 diseases in open-access papers, as found by Europe PMC text mining. Sharing a sentence is not in itself a finding about the gene and the disease. The quoted sentences say what the papers report.
psoriasis (158 papers, 2007 to 2026). An autoimmune condition characterized by red, well-delineated plaques with silvery scales that are usually on the extensor surfaces and scalp. "Following the identification of IL-23R polymorphisms in Crohn’s disease, their associations with other inflammatory disorders, including psoriasis, rheumatoid arthritis (RA), and Behçet’s disease (BD), have been extensively investigated." (PMID 41596568, 2026). "IL23R was the only gene that has been previously associated with psoriasis and other autoimmune diseases." (PMID 39000125, 2024). "The clinical relevance of IL-23R is underscored by its association with an elevated susceptibility or diminished vulnerability to a spectrum of diseases, including psoriasis, ankylosing spondylitis, and inflammatory bowel disease (IBD)." (PMID 39796684, 2024). "The lead psoriasis associated SNP (rs9988642) is in high LD with rs11209026, a missense exonic SNP found within IL-23R." (PMID 38785955, 2024). "Several SNPs associated with psoriasis risk have been found in genomic regions corresponding to both subunits of IL-23 (p19 and p40) and IL23R." (PMID 37628670, 2023). "For example, mutations in the IL-12B, IL-23R, and IL-23A genes are associated with both susceptibility to psoriasis and an increased risk of developing diabetes." (PMID 38179048, 2023). "Sarcoidosis, alongside several other autoimmune disorders, including psoriasis, has been demonstrated to be associated with IL23R polymorphism." (PMID 35163689, 2022). "Lastly, common DNA variants of IL-12B, IL-23R, and IL-23A were associated with increased susceptibility to psoriasis and contributed to an increased risk of developing T2D in a Spanish population." (PMID 36012327, 2022). "Specifically, the IL23R rs11209026-AG genotype was related to greater risk of developing paradoxical psoriasis during treatment (OR = 11,011.59, CI95% = 17.36–6984187.8, p = 0.005)." (PMID 33921427, 2021). "Variations in the IL23 receptor (IL23R) gene are strongly associated with AS and other related conditions such as psoriasis and IBD and have also been linked with juvenile onset psoriatic arthritis but not ERA." (PMID 34136509, 2021). "The impact of polymorphisms in the IL23R gene on the response to anti-TNF drugs in biologic-naive patients diagnosed with moderate-to-severe psoriasis has been evaluated in a study with Spanish patients (n = 109)." (PMID 33921427, 2021). "Sequence variations in IL23R gene have also been associated with the risk of several other immune system-related conditions, like psoriasis and inflammatory bowel disease." (PMID 32113484, 2020). "In an Egyptian cohort, the interaction of the single nucleotide polymorphisms rs610604 (IL-12B) and rs11209026 (IL-23R) showed a significant association with psoriasis." (PMID 33408595, 2020). "SNPs in the regions coding for the IL-23 cytokine (both the p40 and p19 subunit) as well as the IL-23R have been identified to convey psoriasis risk." (PMID 30909615, 2019). "Our study is the first to investigate the relationship between IL-23R gene polymorphisms and psoriasis in Turkey." (PMID 31648514, 2019). "There are many studies evaluating the association between psoriasis and IL-23R rs2201841 polymorphism." (PMID 31648514, 2019). "Previous studies have shown a significant relationship between psoriasis and some polymorphisms in the IL-23R gene." (PMID 31648514, 2019). "This study is also the first investigating the relationship between IL-23R gene polymorphisms and psoriasis in Turkey." (PMID 31648514, 2019). "IL-23R gene polymorphisms and the association of these polymorphisms with serum IL-23 levels were investigated in patients with psoriasis in the current study." (PMID 31648514, 2019). "The primary IL23R association with AS (also psoriasis and IBD) is with rs11209026, a coding SNP in the cytoplasmic tail, which alters IL-23R signaling." (PMID 30687330, 2018).
psoriasis (continued). "It is known that IL-23 and IL-23R are involved in pathogenic Th17 responses, and IL-23R is associated with many autoimmune diseases such as psoriasis, AS, and Crohn’s disease." (PMID 28054948, 2017). "Aside from the MHC components, also a few other genes, specifically those encoding interleukin 23 receptor (IL-23R) and interleukin 12B (IL-12B) were implicated in the pathogenesis of both psoriasis and IBD." (PMID 28905102, 2017). "The key role of this axis in psoriasis pathogenesis is strongly supported by the association between IL-23R, IL-12B, and IL-23A gene variants and psoriasis susceptibility." (PMID 27595115, 2016). "Further, a missense mutation (R381Q) in IL23R was shown to impair IL-23-induced Th17 activation and effector function and confer protection against psoriasis." (PMID 26573299, 2016). "For some loci, this is a stronger effect size (TRAF3IP2, REL, FBXL19); for others, different genetic variants at the same locus predispose to psoriasis and PsA (IL23R) whereas other loci appear specifically associated with PsA (HLA B27, 5q31 locus)." (PMID 26255310, 2016). "The study reveals important insights into the genetics of PsA susceptibility as we find evidence for a distinct PsA variant at the known psoriasis susceptibility locus, IL23R, and we identify a new PsA-specific association at chromosome 5q31." (PMID 25651891, 2015). "Several recent studies have indicated an association between IL-23R polymorphism and some autoimmune diseases, such as inflammatory bowel disease, multiple sclerosis and psoriasis." (PMID 25922796, 2015). "We genotyped seven single-nucleotide polymorphisms (SNPs) in candidate genes of six ILs: IL4, IL10, IL12B, IL13, IL15, and IL23R, which have been shown in the literature to be associated with psoriasis in other ethnic groups." (PMID 24971308, 2014). "IL-23 p40 and p19 are overexpressed in Ps skin, and it has been shown that a hypofunctional variant of IL-23R is protective in psoriasis." (PMID 24286492, 2013). "Further work has shown that a single nucleotide polymorphism (SNP) in the IL-23R) gene on chromosome 1p31 is associated with Crohn’s disease (CD) and psoriasis." (PMID 24286190, 2013). "More recent studies have also revealed that polymorphisms in the IL-12/23p40 and IL-23 receptor (IL-23R) are associated with psoriasis." (PMID 23956763, 2013). "A GWAS performed in a Chinese population (217 cases and 288 controls) identified other polymorphisms associated with psoriasis in IL23R (A allele rs11465817-A allele rs1343152 haplotype) and IL12B (rs6887695)." (PMID 24069534, 2013). "In a GWAS performed in a Thai cohort (206 cases and 144 controls), a marginally significant association was found between rs7530511 (IL23R gene) and psoriasis; rs3212227 (IL23R) was also associated with the disease." (PMID 24069534, 2013). "Genome-wide association studies have shown that the IL23R R381Q gene variant protects against psoriasis, Crohn's disease and ankylosing spondylitis." (PMID 21364948, 2011). "One of the most robust genetic findings is the association of a variant in the IL23R gene with CD, psoriasis and AS." (PMID 21364948, 2011). "Genetic studies have shown that the less common A allele of the IL23R confers approximately threefold protection against developing CD and twofold protection against psoriasis and AS." (PMID 21364948, 2011). "This study also identified two missense SNP in IL-23R associated with psoriasis, one of which (rs11209026, Arg381Gln) is also associated with Crohn's disease." (PMID 20606885, 2010). "Association of IL23R with IBD was replicated in our Swedish patients, and linkage and association of the IL23R region with psoriasis was found in the Finnish population." (PMID 19175939, 2009). "For instance, while association of the IL23R gene with inflammatory bowel disease, psoriasis and ankylosing spondylitis has been shown before, only recently has its involvement also been linked to MS." (PMID 20041220, 2009).
psoriasis (continued). "Independent associations of psoriasis and psoriatic arthritis with both IL23R and a SNP 4 kb upstream of IL12RB2, indicate that extended studies in this gene cluster would be relevant to other chronic inflammatory diseases as well." (PMID 19175939, 2009). "It is also the first study to demonstrate linkage and association of the IL23R region with psoriasis in the Finnish population." (PMID 19175939, 2009). "It is also the first study to report linkage and association of the IL23R region with psoriasis in the Finnish population." (PMID 19175939, 2009). "Recent reports have confirmed association of single-nucleotide polymorphisms (SNPs) mapping to the interleukin-23 receptor (IL-23R) and IL-12β genes with psoriasis susceptibility." (PMID 19035472, 2008). "In this large case–control study, we observed that polymorphisms in the IL12B and IL23R genes, both of which were previously associated with psoriasis, are also associated with susceptibility to PsA." (PMID 19035472, 2008). "Key genetic loci such as HLA-C, TNIP1, IL12B, and IL23R are linked to psoriasis." (PMID 40557155, 2025). "For example, certain genetic variants of the IL23R may contribute to the increased incidence of psoriasis in ankylosing spondylitis, ulcerative colitis, and Crohn’s disease patients." (PMID 39000125, 2024). "Also, IL23R (interleukin-23 receptor) gene polymorphism is associated with inflammatory bowel disease, psoriasis, and ankylosing spondylitis." (PMID 38956704, 2024). "From a genetical point of view, the overlap between psoriasis and MetS may be explained by IL-12B, IL-23R, and IL-23A gene variants related to psoriasis susceptibility but also to risk for developing type II DM." (PMID 38003284, 2023). "In a later GWAS comprising more than 10,000 individuals, association of IL23R variants with psoriasis could be confirmed." (PMID 38835412, 2023). "Likewise, a large-scale genome-wide association study (GWAS) for psoriasis showed that the variants of IL-23R are significantly associated with psoriasis susceptibility." (PMID 36012327, 2022). "Further, this IL23R association is recapitulated in other diseases, such as psoriasis and inflammatory bowel disease (IBD), which commonly occur in individuals with AS and/or their relatives, highlighting a degree of shared genetic background between these conditions." (PMID 33746951, 2021). "In particular, the IBD3 locus involved in CD and UC, and the PSORS1 locus involved in psoriasis, were found in the 6P21 region, and the gene encoding the interleukin 23 receptor (IL-23R) and interleukin 12B (IL-12B) are both implicated in the pathogenesis of psoriasis and IBD." (PMID 33477990, 2021). "Furthermore, the association between IL23R polymorphisms and the risk of developing toxicity and/or paradoxical psoriasis due to the anti-TNF medication has been demonstrated in a study with Spanish patients (n = 161)." (PMID 33921427, 2021). "Furthermore, genetic variants in IL23R are associated with multiple immune-related diseases such as Behcet’s disease, Crohn’s disease, ulcerative colitis, psoriasis, and ankylosing spondylitis." (PMID 32437414, 2020). "Various studies have reported a single-nucleotide polymorphism in IL23R both in psoriasis and IBD." (PMID 32987907, 2020). "Further studies are needed to investigate IL-23R polymorphisms in serum and skin lesions together with IL-17 levels and to evaluate more candidate IL-23R gene polymorphisms in larger groups of patients with psoriasis." (PMID 31648514, 2019). "Among them, genetic findings highlighted the importance of IL-23 signaling and the T17 differentiation in psoriasis as some genetic variants of both IL-23 subunits and IL-23R genes confer predisposition to the disease, whereas an IL-23R variant protects against psoriasis." (PMID 29316717, 2018).